SCN1A (sodium voltage-gated channel alpha subunit 1)
Diseases named in the same sentence as SCN1A in open-access papers (continued):
Sharing a sentence is not in itself a finding about the gene and the disease.
epilepsy (continued). "Our study suggests the findings of this investigation indicate that the polymorphisms SCN1A rs2298771 and SCN2A rs17183814 could potentially act as predictive biomarkers for the responsiveness to VPA among Chinese epilepsy patients." (PMID 38837984, 2024). "We investigated SCN1A mRNA expression and expression of two SCN1A related antisense RNAs in brain tissues in different age groups of pediatric non-Dravet patients who underwent surgery for drug resistant epilepsy." (PMID 38283997, 2024). "One report regarding Japanese patients with epilepsy found that SCN1A rs3812718 was associated with resistance to CBZ but not the dose of CBZ." (PMID 39228521, 2024). "Identifying patients with epilepsy who would derive the greatest benefit from VPA therapy may involve the consideration of SCN1A rs3812718 and SCN2A rs2304016 genotypes." (PMID 38837984, 2024). "There are SCN1A mutations with both FHM and epilepsy, like L263Q, T1174S, Q1489H, and L263V." (PMID 38255689, 2024). "In fact, pathogenic variants of SCN1A/NaV1.1, SCN2A/NaV1.1, SCN3A/NaV1.1, SCN8A/NaV1.6, and SCN1B/β1, which are expressed in the central nervous system, are important causes of different types of epilepsies, including mild and severe forms." (PMID 37654020, 2024). "In this context, it also should be underlined that we did not investigate brain tissues from SCN1A positive patients as these do not qualify for epilepsy surgery as investigated previously." (PMID 38283997, 2024). "For example, SCN1A is a commonly detected epilepsy gene in DS patients." (PMID 36980114, 2023). "Different mutations in SCN1A gene have been identified to cause monogenic clinical phenotypes of epilepsy in addition to more common nonmonogenic epilepsies." (PMID 36987424, 2023). "A recent survey of eight patients suggested that only patients with a milder phenotype of SCN1A-related epilepsy than DS may profit from resective epilepsy surgery in some circumstances (Vezyroglou and others 2020)." (PMID 35414300, 2023). "The present study aimed to determine whether Gpr55 affects the epilepsy phenotype of F1.Scn1a+/- mice to infer its potential as a new drug target for the treatment of Dravet syndrome." (PMID 36701411, 2023). "In family 1, the c.4224G > C variant in the SCN1A gene existed in the proband and was absent in his healthy father and mother, which can explain the symptom of epilepsy." (PMID 38025388, 2023). "Dravet syndrome (DRVT) is a rare form of neurodevelopmental disorder with a high risk of sudden unexpected death in epilepsy (SUDEP), caused mainly (>80% cases) by mutations in the SCN1A gene, coding the Nav1.1 protein (alfa-subunit of voltage-sensitive sodium channel)." (PMID 36672274, 2023). "Thus, we examined the functional implications of these observations by investigating the impact of heterozygous genetic deletion of Gpr55 on the epilepsy phenotype of F1.Scn1a+/- mice." (PMID 36701411, 2023). "More specific KCNT1 channel blockers may be more effective for treatment of KCNT1, SCN8A, and SCN1A epilepsy." (PMID 37901435, 2023). "The prevalence of ictal vocalizations may provide diagnostic utility in epilepsy patients, so we aimed to determine whether GTCS in the Scn1a+/− mouse model of Dravet syndrome is also associated with vocalizations." (PMID 36811143, 2023). "Examples of a genetic link include epilepsy associated with KCNQ2, CDKL5, and SCN1A mutations." (PMID 37928141, 2023). "The SCN1A-A3184G (p.Thr1067Ala) polymorphism has been suggested to be linked with the epilepsy risk in several non-Caucasian populations." (PMID 37679850, 2023). "Mutations in VGSCs (such as in SCN1A, SCN2A, SCN3A, and SCN8A) can lead to defects in inactivation gating, enhancing persistent sodium currents (INaP) and firing of neurons, resulting in epilepsy and ataxia." (PMID 40217485, 2023).
epilepsy (continued). "Furthermore, the clinical phenotype of SCN1A disorders has expanded to include hemiplegic migraine which possesses a quite distinct pathophysiological basis to epilepsy, suggesting diverse pathways to neural circuit dysfunction." (PMID 37139072, 2023). "The identified missense mutation c.1603C>T and p.R535C in the SCN1A gene (NM_001165963.1) a pathogenic variant identified in Saudi patients with epilepsy has not been reported previously." (PMID 35813387, 2022). "In our preliminary research, we investigated the patterns and frequencies of SCN1A-A3184G alleles and genotypes among Egyptian children and adolescents with non-lesional epilepsy." (PMID 36056404, 2022). "This study aims to assess saliva and urine pH in children with SCN1A-related epilepsy." (PMID 36237607, 2022). "After searching in DrugBank, we retrieved a total of 47 anti-epileptic drugs and 151 targets, of which identified 17 target genes (CACNA1A, CHRNA4,CHRNA7,GABRA1,GABRA2,GABRB2,GABRG2,GRIK1,GRIN1,GRIN2B,KCNQ2,KCNQ3,SCN1A,SCN2A, SCN3A,SCN8A and SCN9A) were overlapped with risk genes of epilepsy." (PMID 36006933, 2022). "Thirty-five patients manifested epilepsy without any other comorbidity and seven of them (20.0%) carried variants in six genes, namely KCNQ2, NALCN, PAK3, PRRT2, SCN1A, and SLC2A1 that are among the well-known genes causing epilepsies or syndromes including epilepsy." (PMID 36035117, 2022). "Although Scn1a+/- mice exhibit multifocal epilepsy, temperature-induced seizures have been shown to prominently emanate from the temporal lobe, and focal hippocampal Nav1.1 reduction is sufficient to confer temperature-sensitive seizure susceptibility in conditional Scn1a+/- mice." (PMID 35212623, 2022). "After analyzing exome data of VI:3, VI:40, and VII:10 of Family 047, we observed a missense variant in SCN1A (c.3530C > G; p.(Pro1177Arg)) present in individuals with epilepsy (VI:3 and VI:40) but not in the unaffected individual VII:10." (PMID 35627139, 2022). "Therefore, it is urgent for clinicians, especially epilepsy specialists to fully understand these genes involved in DS in addition to SCN1A." (PMID 35359639, 2022). "In the current research, we investigated the patterns and frequencies of SCN1A-A3184G (p.Thr1067Ala) polymorphism among Egyptian children and adolescents with non-lesional epilepsy, including both AEDs responders and resistant cases." (PMID 36056404, 2022). "Any mutation in the SCN1A gene causes mild to severe type of epilepsies known as DS that occur due to de novo mutation first time in a person with epilepsy with no family history." (PMID 35813387, 2022). "This study enriches the genotypes and phenotypes of SCN1A-related epilepsy." (PMID 35663268, 2022). "Therefore, we aimed to assess the pH of saliva and urine in a series of patients with SCN1A-related epilepsy." (PMID 36237607, 2022). "Furthermore, the rs13405797 of SCN1A and rs2119067 of SCN3A can be considered as epilepsy risk biomarkers within individuals have a family history of epilepsy." (PMID 35801810, 2022). "No significant mutation in exon 26 of SCN1A was observed in this study which is consistent with the fact that there are no mutations reported in exon 26 of the SCN1A gene causing drug-resistant epilepsy." (PMID 35136380, 2022). "However, multiple lines of evidence suggest that the pathophysiology of epilepsy in Scn1a+/- mice is more complex than impairment of inhibition." (PMID 35212623, 2022). "Patients with SCN1A-related epilepsy were divided into two groups according to whether they had seizures during the study." (PMID 36237607, 2022). "As genetic studies have identified >700 mutations in genes that code for voltage-gated sodium channels in epilepsy, and reports of GATOR1 and Scn1A mutations contributing to temporal epilepsy, our data now implicate the NPRL2 and mTORC1 regulatory pathways in controlling Scn1a expression." (PMID 35165201, 2022).
epilepsy (continued). "We investigated the SCN1A-A3184G polymorphism among Egyptian children and adolescents with non-lesional epilepsy." (PMID 36056404, 2022). "Dominant pathogenic variations in the SCN1A gene are associated with several neuro developmental disorders with or without epilepsy, including Dravet syndrome (DS)." (PMID 34917021, 2021). "Despite these promising results, mutation studies of SCN2A in patients with seizure disorders have not shown clearly defined phenotypes unlike SCN1A and SCN8A." (PMID 33841294, 2021). "In addition to epilepsy, hemiplegic migraine, ASD, sudden death, and arthrogryposis multiplex congenital can also be caused by mutations of SCN1A." (PMID 35002916, 2021). "Results from the comparison between all patients with epilepsy and all control individuals revealed a number of genome-wide significant SNPs at 2q24.3 (p = 8.71 × 10−10), implicating SCN1A (a sodium ion channel subunit gene), and at 4p15.1 (p = 5.44 × 10−9), implicating PCDH7 (a protocadherin gene)." (PMID 34573423, 2021). "To determine whether Trpv1 expression may contribute to the epilepsy phenotype of Scn1a+/− mice, we compared the cortical mRNA levels from WT and Scn1a+/− mice on both 129S6/SvEvTac and on [129S6/SvEvTac × C57BL/6J]F1 (129 × B6) genetic backgrounds." (PMID 34079465, 2021). "This heterogeneity makes SCN1A epilepsies extremely challenging to treat, as a medication that improves seizures in one patient may exacerbate them in another." (PMID 34925043, 2021). "Other described mutations include CNTNAP2 (Contactin-associated protein-like 2) and SCN1A (sodium channel, voltage-gated, type I, alpha subunit), which might point that EAF pertains to the spectrum of SCN1A-related epilepsy." (PMID 35153984, 2021). "The disorder, which was first reported fifty years ago by Juberg and Hellman, represents one of the most diffuse monogenetic epileptic forms in the pediatric population, and recent molecular epidemiologic studies indicate PCDH19 as the second most clinically relevant gene in epilepsy after SCN1A." (PMID 34201522, 2021). "In addition to epilepsy, FHM3, SHM, ASD, sudden death, and AMC can also be caused by SCN1A mutations." (PMID 35002916, 2021). "Clinical data and mutation sites or chromosomal deletions in SCN1A-associated non-dravet syndrome epilepsy." (PMID 35002916, 2021). "This may reflect how some gene-defined epilepsies are relatively similar early in the disease but evolve with variable types of seizures and outcomes, for example SCN1A-related epilepsies, which include Dravet syndrome and Febrile Seizures plus." (PMID 34031551, 2021). "Some mutations of ion channels, such as SCN1A and SCN2A, are known to be associated with GEFS+, and some mutations of ion channels were also presumed to be associated with sudden unexpected death in epilepsy and cardiac arrhythmia." (PMID 33212914, 2020). "SCN1A-related epilepsies identified in clinical patients through WES and/or NGS." (PMID 33013363, 2020). "However, targeted gene panel sequencing for SCN1A, SCN2A, and GABRG2, which are associated with GEFS+, showed no pathogenic mutations in the 11 children subsequently diagnosed with epilepsy in this study." (PMID 33212914, 2020). "Finally, SCN1A and SCN8A mutations have been associated with sudden unexpected death in epilepsy (SUDEP)." (PMID 31185666, 2019). "Topiramate, another sodium channel blocker to bind SCN1A, is approved to treat seizure disorders." (PMID 32063857, 2019).
epilepsy (continued). "All people had previously undergone diagnostic genetic screening for variants in epilepsy-associated genes including SCN1A, but no clear causal variant had been identified." (PMID 31814998, 2019). "As in much of epilepsy genetics, SCN1A is among the best studied in this regard." (PMID 31819908, 2019). "In the present study, we advanced the classification of missense mutations found in one of the most relevant genes in the context of clinical testing in the epilepsies, SCN1A, by modifying the ACMG/AMP criteria and combining them into a classification workflow specific for DS." (PMID 31001185, 2019). "Given that the predominant expression of Nav1.1 is in inhibitory neurons and that of Nav1.2 is in excitatory neocortical/hippocampal neurons, it seems reasonable that SCN1A loss- or SCN2A gain-of-function mutations lead to epilepsies." (PMID 30175250, 2018). "Therefore, we performed qRT-PCR for Scn1a and Scn8a, coding for the voltage-gated sodium channels Nav1.1 and 1.6, as well as for the epilepsy gene Scn2a, coding for Nav1.2, in brain lysates from weaned and 5-month-old mice." (PMID 29046322, 2017). "The correlation between SCN1A IVS5-91G > A polymorphism and maximum doses of Oxcarbazepine (OXC) may have a potential effect on resistant to epilepsy." (PMID 28202008, 2017). "After removing SCN1A from the set of M30 genes, the enrichment of association between M30 and epilepsy remained significant for both focal (FE: enrichment P = 0.0019, Z-score = 2.88) and generalised (GGE: enrichment P = 0.0097, Z-score = 2.34) epilepsy." (PMID 27955713, 2016). "Analysis of M30 expression revealed consistent downregulation in the epileptic brain in heterogeneous forms of epilepsy including human temporal lobe epilepsy, a mouse model of acquired temporal lobe epilepsy, and a mouse model of monogenic Dravet (SCN1A) disease." (PMID 27955713, 2016). "The Scn1a+/- mouse model has a strain-dependent epilepsy phenotype." (PMID 27768696, 2016). "In Dravet syndrome, as well as in other SCN1A-related seizure disorders, sodium channel blockers such as carbamazepine, lamotrigine, phenytoin are contraindicated as they may increase frequency and severity of seizures." (PMID 27242528, 2016). "SCN1A mutations also lead to genetic epilepsy with febrile seizures plus (GEFS+), which is an inherited disorder characterized by FSs that persist beyond 6 years of age and the development of adult epilepsy." (PMID 27799911, 2016). "SCN1A mutations also lead to genetic epilepsy with febrile seizures plus (GEFS+), which is an inherited disorder characterized by early-life FSs and the development of a range of adult epilepsy subtypes." (PMID 27799911, 2016). "Functionally significant association of drug target genes such as GABRG2 and SCN1A and efflux transporter gene ABCB1 to susceptibility to epilepsy in the present population needs to be seen in combination rather than isolation in evaluating therapeutic response." (PMID 24586633, 2014). "Their encephalopathy is not a pure consequence of epilepsy, but SCN1A mutation seems to play an additional direct role." (PMID 24225340, 2013). "Furthermore, epilepsy models with SCN1A defects have identified functional deficits in GABAergic interneurons, but not in pyramidal neurons." (PMID 23639079, 2013). "A hundred children with severe epilepsy were divided into Dravet syndrome and non-Dravet syndrome groups and screened for SCN1A mutations by direct sequencing." (PMID 22848613, 2012). "SCN1A, SCN2A, and SCN3A gene mutations may give rise to epilepsy and epileptic/convulsive disorders." (PMID 22798951, 2012). "They showed that two DS children carrying SCN1A truncating mutations had their cognitive performance continued to deteriorate irrespective of the difference in their epilepsy severities." (PMID 22848613, 2012).
epilepsy (continued). "The SCN1A gene is a major gene in different epilepsies and epilepsy syndromes; the HRM could be the new methodology, more rapid and efficacious, for molecular analysis of the SCN1A gene." (PMID 21713554, 2011). "Rather these could be linked more appropriately with a specific disease and in the case of SCN1A gene, it is epilepsy." (PMID 19099596, 2008). "In Dravet syndrome specifically, PRS for intelligence, longevity, and epilepsy were significantly different to those seen in non‐SCN1A‐related epilepsy without other known monogenic causes;14 a polygenic background influences epilepsy phenotype in monogenic families." (PMID 40836506, 2026). "SCN1A-related epilepsy may present in siblings with febrile and afebrile seizures." (PMID 42311771, 2026). "Importantly, this distinction has therapeutic implications, as sodium channel blockers, which are usually the treatment of choice for focal seizures, may worsen seizures in SCN1A-related epilepsy." (PMID 41573391, 2025). "Polymorphisms in the SCN1A and SCN2A, genes associated with Dravet syndrome and febrile seizures were found with statistical significance in patients with FIRES indicating that an undiagnosed seizure disorder could be the cause." (PMID 40310164, 2025). "This case highlights the potential for adult-onset phenotypic progression in SCN1A-related epilepsy and may broaden the clinical spectrum of DS, underscoring the importance of ongoing surveillance during adulthood, particularly in patients with rare or novel SCN1A missense variant (p.Gly1371Asp)." (PMID 41158906, 2025). "Previous studies of genotype‐phenotype correlations for SCN1A variants have not systematically included functional assessments and do not provide a representative cross section of SCN1A variants identified by present day genetic testing paradigms utilized in individuals with new onset epilepsy." (PMID 39838578, 2025). "SCN1A LoF variants include Dravet syndrome, a severe drug-resistant developmental and epileptic encephalopathy in which sodium channel blockers are contraindicated, and genetic epilepsy with febrile seizures plus (GEFS+), a milder drug-responsive epilepsy form." (PMID 39200163, 2024). "The aim of the present study was to investigate whether cis-acting long non-coding RNAs (lncRNAs) of SCN1A are expressed in brain specimens of children and adolescent with epilepsy as these molecules comprise possible targets for precision-based therapy approaches." (PMID 38283997, 2024). "Like SCN1A LOF variants in Dravet syndrome, recent studies described the expression of NaV1.2 channels in inhibitory neurons, indicating the mechanism of epilepsy due to SCN2A loss-of-function variants could also be the imbalance of excitatory/inhibitory neurons." (PMID 37152433, 2023). "However, the genotype–phenotype correlation in epilepsy patients with SCN1A variants is not definite enough." (PMID 38025388, 2023). "At present, voltage-gated sodium channel genes such as SCN1A, SCN2A, SCN3A, and SCN8A were reported to be causative genes of epilepsy, among them SCN2A has been reported to be the second most common, next only to SCN1A, the first reported causative gene for epilepsy." (PMID 35431799, 2022). "Future studies to extend our present findings using a model of adult-onset acquired TLE into syndrome-specific models of epilepsy, such as pediatric genetic epileptic encephalopathies (i.e., SCN1A+/− models of Dravet syndrome), could expand the generalizability of our current findings." (PMID 35163358, 2022). "Chronically increased neuronal excitation might lead to the excitatory synapse dependent activation of the eEF2K/eEF2 pathway and the subsequent dampening of the GABAergic synapses would further increase network activity, thereby aggravating the epilepsies in the Scn1a ± mice." (PMID 34980259, 2022). "Thus, we chose a non-invasive method to measure the pH in children with SCN1A-related epilepsy." (PMID 36237607, 2022).